RTEL1 (regulator of telomere elongation helicase 1)
Diseases named in the same sentence as RTEL1 in open-access papers (continued):
Sharing a sentence is not in itself a finding about the gene and the disease.
sarcoidosis (1 paper, 2019). Sarcoidosis is a multisystemic disorder of unknown cause characterized by the formation of immune granulomas in involved organs. "RTEL1 mutation has been evidenced in 5%–9% of cases of familial pulmonary fibrosis; patients with ILD and RTEL1 mutations present with various pulmonary and extra-pulmonary phenotypes, including sarcoidosis and RA-ILD." (PMID 31248154, 2019).
thrombophilia (1 paper, 2023). A condition characterized by an abnormally high level of thrombi. "CD320, RTEL1, UCP2, APOA5 and PROZ participate in healthy-specific or disease-specific subnetworks involving thrombophilia-annotated genes and are related to general thrombophilia mechanisms according to the literature." (PMID 37098010, 2023).
viral disease (1 paper, 2017). "We therefore assume that the observed susceptibility to viral disease in RTEL1 deficiency and likely in other DC-subtypes may be a consequence of T-cell exhaustion upon repeated proliferation stimuli triggered by infections." (PMID 28507545, 2017).
Xeroderma pigmentosum complementation group D (1 paper, 2021). Xeroderma pigmentosum complementation group D (XPD) is a subtype of xeroderma pigmentosum (XP; see this term), a rare photodermatosis predisposing to skin cancers. "Fe-S family helicases, including FANCJ, DDX11/ChlR1, xeroderma pigmentosum complementation group D (XPD), and regulator of telomere elongation helicase 1 (RTEL1), are closely related to G4 function modulation." (PMID 34912850, 2021).
xerosis (1 paper, 2024). "Notably, the mother affected by cutaneous xerosis carried the same rare RTEL1 variant." (PMID 38791074, 2024).
cancer (24 papers, 2013 to 2025). A tumor composed of atypical neoplastic, often pleomorphic cells that invade other tissues. "We introduced an ATPase-dead mutation (K48R) into the endogenous RTEL1 loci to determine how the loss of ATPase activity affects cellular RTEL1 and cancer cell growth." (PMID 40087886, 2025). "While RTEL1 deficiency results in the degeneration of various cellular compartments, the mutation is also associated with an increased risk of cancer development." (PMID 36253342, 2023). "Regulator of telomere elongation helicase 1 (RTEL1), a telomere length‐related gene, is closely linked to cancer and age‐related diseases." (PMID 30623606, 2019). "A number of GWASs and candidate gene studies have identified RTEL1 variants involved with genetic predispositions to cancers development." (PMID 31762827, 2019). "Cancer genome-wide association studies (GWAS) showed that RTEL1 polymorphisms contribute to LC risk." (PMID 27765928, 2016). "Furthermore, analyses of mutated protein structures, evolutionary conservancy, surface accessibility, domains & PTM sites, cancer susceptibility, and interatomic interaction revealed the detrimental effect of these 11 nsSNPs on RTEL1 protein." (PMID 39240887, 2024). "This raises the possibility that RTEL1 is partially redundant: there may be other molecule(s) whose functions overlap with those of RTEL1 and may compensate for RTEL1 deficiency in surviving cancer cells." (PMID 36253342, 2023). "Recent studies revealed that RTEL1 might act as a cancer susceptibility gene and implicated in a number of telomere dysfunction syndromes." (PMID 35184406, 2022). "Nevertheless, it is too early to speculate whether, in analogy to genomic instability syndromes, RTEL1 deficiency might be associated with an increased cancer predisposition manifesting later in life." (PMID 28507545, 2017). "The emergence of RTEL1 variants associated with predisposition to cancers has confirmed the hypothesis that genetic factors underlying telomere length have an especially strong influence on cancer development." (PMID 31762827, 2019). "In this study, we investigated the cellular dynamics and telomere recruitment of RTEL1 in cultured human cancer cells." (PMID 40087886, 2025). "In summary, our study presents a new model for the dynamic recruitment of RTEL1 to telomeres, demonstrates the importance of its ATPase activity in cancer cell survival, and proposes a strategy for targeting RTEL1 for cancer intervention." (PMID 40087886, 2025). "Regulators of telomere elongation helicase 1 (RTEL1) are of high interest because RTEL1 is related to the telomere region, which contributes to cancer cell proliferation." (PMID 40564899, 2025). "The low copy number of RTEL1, in conjunction with the multiple defects in cells harboring the catalytically dead mutant, highlights the essential role of low-abundance proteins such as RTEL1 in telomere preservation and the proliferation of cancer cells." (PMID 40087886, 2025). "Our study shows that inhibiting RTEL1 ATPase activity can significantly slow cancer cell growth, offering a promising mechanism of action for future RTEL1-targeted treatments." (PMID 40087886, 2025). "The engineered Telomouse reported here demonstrates a dominant role of RTEL1 in telomere length regulation and provides a unique model for aging and cancer." (PMID 37872177, 2023). "Overall, our data highlight a previously unsuspected role of RTEL1 and Poldip3 in R-loop suppression at genomic regions where transcription and replication intersect, with implications for human diseases including cancer." (PMID 32561545, 2020). "RTEL1 plays a crucial role in cancers, including LC, and in hereditary diseases, such as Hoyeraal–Hreidarsson syndrome." (PMID 27765928, 2016). "In many cellular circumstances, it is conceivable that either overexpression or downregulation of the RTEL1 gene could lead to the formation of cancer or tumorigenesis in many different ways." (PMID 39240887, 2024).
cancer (continued). "We identified 42 germline variants of interest in 58 of 9089 TCGA participants (0.6%) across all cancer entities, including 8 variants present in the NCI’s TBD cohort (4 loss of function and 4 missense affecting either CTC1, RTEL1, TERT, or WRAP53) (eTable 5 and eTable 15 in Supplement 1)." (PMID 39661387, 2024). "Thus, the complex‐forming interaction of SLX4 with RTEL1 is required for normal RF progression; abolition of this interaction is observed in patients with cancer and HHs, respectively." (PMID 36253342, 2023). "IRF8, RTEL1, and FCGR3A mutations have been observed in NKD patients but their association with cancer is unknown." (PMID 31379882, 2019). "IRF8, RTEL1, and FCGR3A mutations are associated with NKD but their associations with cancer are unknown." (PMID 31379882, 2019). "Yet, it is rather difficult to assess cancer predisposition in patients succumbing early in life or when RTEL1 deficiency does not affect global genome integrity." (PMID 28507545, 2017). "With the evidence discussed in this section regarding the roles of RTEL1 in telomere maintenance and the beneficial role of intact telomeres in maintaining the survival capacity of cancer cells, it seems probable that RTEL1 may act through these mechanisms to facilitate carcinogenesis." (PMID 36253342, 2023). "When they are present in human cancers, the duplications with distant intrachromosomal insertion appear to correlate with the frequency of simple deletions of medium and large size, reminiscent of the marked increase in deletions of more than 10 kb seen in the Rtel1 knockout lines here." (PMID 29351848, 2018). "However, as indicated by human genetic data, the RTEL1 genomic locus (20q13.3) is frequently amplified in human cancers, and ted RTEL1 upregulation could be important for tumorigenesis." (PMID 27765928, 2016). "The cancers have been observed in NKD patients with GATA2 and MCM4 mutations although not in patients with IRF8, RTEL1, and FCGR3A mutations." (PMID 31379882, 2019). "Ht-REC likely contributes to complex genome rearrangements in the absence of mammalian RTEL1 and in cancer." (PMID 29351848, 2018).
tumor (16 papers, 2011 to 2025). "Cross comparison of our DEGs to a E2F1 cistrome revealed many E2F1 target genes (E2f7, Rtel1, Myc, Ybx3 and Id3) being downregulated in β1 integrin-deficient tumours, consistent with slow tumour growth phenotype." (PMID 34782719, 2022). "Conversely, overexpression of RTEL1 depletion significantly hindered cell proliferation and colony formation, further supporting its tumor genesis function." (PMID 38532312, 2024). "To better understand tumor genesis activity of RTEL1, we took an RNA-sequence assay, the result showed that RTEL1 knockdown resulted in upregulation or downregulation of numerous target genes." (PMID 38532312, 2024). "The potential explanation for RTEL1 acting as a tumor promoter hypothetically comes from understanding its functions at the molecular level in several directions." (PMID 36253342, 2023). "Whether tumor recurrence is related to mutations in MKNK1, POLE, RET, RTEL1, RUNX1T1, TAP1 still requires further research for validation." (PMID 40901169, 2025). "RTEL1 knockdown significantly suppressed tumor growth compared with the control." (PMID 38532312, 2024). "However, among the class III gene mutation testing results, the genes with higher abundance mutations include MKNK1, POLE, RET, RTEL1, RUNX1T1, TAP1, indicating that these gene mutations may be related to sex-cord-stromal tumors or require further research to explore unknown tumor subtypes." (PMID 40901169, 2025).
infection (6 papers, 2016 to 2023). The state of being infected such as from the introduction of a foreign agent such as serum, vaccine, antigenic substance or organism. "Given we saw the potential for small variations in DAOTA-M2 lifetime after infection, the null infected samples were used as our basis for comparison for RTEL1 mutants." (PMID 33420085, 2021). "Infection of cells with a Cre-GFP-expressing adenovirus, but not a GFP-expressing control, results in loss of the floxed Rtel1 allele and the subsequent elimination of RTEL1 protein." (PMID 33357438, 2020).
genetic diseases (4 papers, 2016 to 2025). "Nevertheless, long-term treatment with such an inhibitor should be approached with caution, given the adverse effects noted in inherited diseases linked to RTEL1 mutations." (PMID 40087886, 2025). "Several mutations in the human Rtel1 gene have been associated to genetic diseases, such as familial Pulmonary Fibrosis and Hoyeraal‐Hreidarsson syndrome, a severe form of Dyskeratosis Congenita characterized by accelerated telomere shortening and a multisystem bone‐marrow failure." (PMID 39180489, 2024).
haematological disorders (3 papers, 2018 to 2025). "Heterozygous variants in RTEL1, which encodes a protein involved in TERC processing and critical for telomere homeostasis, were also observed in hematological malignancies." (PMID 39940930, 2025).
adenocarcinoma (2 papers, 2016 to 2022). A common cancer characterized by the presence of malignant glandular cells. "Thus, we suggest that amplification of RTEL1 may have age-specific function and an important role in adenocarcinoma of intestinal type, which corroborates with the hypothesis that these two histological types have different genetic pathways." (PMID 27366209, 2016).
gastrointestinal tumors (2 papers, 2012 to 2024). "The RTEL1 locus is amplified in many human tumors and upregulation of RTEL1 led to liver malignancies in mice." (PMID 22848695, 2012).
RTEL1 also shares sentences with these, for which no sentence is quoted: astrocytoma (5 papers); breast carcinoma (4); bone marrow failure syndrome (3); brain tumors (2); inflammatory bowel disease (2); myeloid malignancies (2); pneumonia (2); prostate carcinoma (2); 22q11.2 deletion syndrome (1); adrenocortical carcinoma (1); age (1); allergic rhinitis (1); Ataxia (1); atopic dermatitis (1); atrial fibrillation (1); autoinflammatory syndrome (1); brain cancer (1); breast tumor (1); cardiovascular disease (1); Combined immunodeficiencies (1); complement deficiencies (1); Cowden syndrome (1); Crohn disease (1); degenerative disease (1); dermatitis (1); diabetes (1); Dubowitz syndrome (1); Dyskinesia (1); Dystonia (1); endometrial cancer (1).
A further 32 diseases each share a sentence with RTEL1 in 1 paper.